SNORD116-20 (small nucleolar RNA, C/D box 116-20)
Synonyms: HBII-85-20
Gene: Small nucleolar RNA gene on chromosome 15 (25,087,662 to 25,087,753, forward strand). Ensembl gene ENSG00000278715.
Gene Ontology:
Biological process: RNA processing
Cellular component: nucleolus
Homologues: Orthologues: macaque SNORD116 (99% identical), guinea pig SNORD116 (89% identical), guinea pig SNORD116 (85% identical). Paralogues in human: SNORD116-17 (99% identical), SNORD116-19 (99% identical), SNORD116-14 (98% identical), SNORD116-15 (98% identical), SNORD116-18 (98% identical), SNORD116-21 (98% identical), SNORD116-22 (98% identical), SNORD116-16 (96% identical), SNORD116-12 (92% identical), SNORD116-23 (92% identical), SNORD116-24 (92% identical), SNORD116-11 (89% identical), and 20 more.